STAT1 (signal transducer and activator of transcription 1)
Diseases named in the same sentence as STAT1 in open-access papers (continued):
Sharing a sentence is not in itself a finding about the gene and the disease.
glioma (continued). "Ingenuity Pathway Analysis (IPA) demonstrated that CPVL silencing activated the IFN-γ/STAT1 signaling pathway, thereby inducing glioma cell apoptosis." (PMID 34784299, 2021). "Studies have also shown that the expression of STAT1 is decreased in glioma compared with normal brain tissues." (PMID 34276757, 2021). "In direct contrast, a more recent study showed that IL-8 secreted by glioblastoma and other microenvironmental immune cells promotes glioma migration, invasion, and mesenchymal transition via the STAT1/HIF-1α/Snail cascade." (PMID 33498872, 2021). "For example, exogenous overexpression of STAT1 was initially described to decrease proliferation and migration and increase apoptosis in glioma cells." (PMID 33498872, 2021). "IPA revealed that the IFN-γ/STAT1 signaling pathway is a downstream target pathway affected by CPVL that results in glioma cell apoptosis." (PMID 34784299, 2021). "The present study has determined that CPVL silencing can significantly activate the IFN-γ/STAT1 signaling pathway, resulting in the apoptosis of glioma cells." (PMID 34784299, 2021). "Taken together, these results show that CPVL silencing induced glioma cell apoptosis via activating STAT1 signaling pathway." (PMID 34784299, 2021). "Clinical and experimental studies also showed the abnormal expression and dysfunction of STAT1 in glioma." (PMID 34784299, 2021). "Analysis by iRegulon predicted YY1 (Yin Yang 1) and STAT1 (Signal Transducer and Activator of Transcription) to be possible regulators of a number of proteins that are upregulated in the early grades of glioma." (PMID 34900729, 2021). "The results showed higher expression of the STAT1 signaling pathway downstream response genes in the low-grade (WHO I/II) glioma group compared with the high-grade (WHO III/IV) glioma group." (PMID 34784299, 2021). "Survival analysis indicated that the upregulation of STAT1/2/3/5A/6 and downregulation of STAT5B expression was associated with poorer overall survival in glioma." (PMID 34276757, 2021). "In glioma, previous studies showed that the expression of STAT1 was negatively correlated with the grade of glioma." (PMID 34276757, 2021). "Our findings reveal the crucial role of CPVL in promoting the progression of glioma through suppressing STAT1 phosphorylation." (PMID 34784299, 2021). "Previous studies have demonstrated that the IFN-γ/STAT1 signaling pathway plays important roles in glioma apoptosis." (PMID 34784299, 2021). "Analysis of regulatory effects based on IPA software found that CPVL was involved in the regulation of apoptosis of glioma cells through the IFN-γ/STAT1 signaling pathway." (PMID 34784299, 2021). "To determine the possible contribution of STAT1 in glioma progression, we analyzed STAT1 expression in various datasets using the GlioVis platform; STAT1 expression was upregulated with increasing grades of glioma." (PMID 34771447, 2021). "Western blot was used to detect the phosphorylated forms of MAPK family members (ERK1/2, JNK and p38 MAPK), AKT and JAK‐STAT family members (JAK1 and STAT1) in glioma cells which transfected with NC and KLHDC8A siRNA." (PMID 32851798, 2020). "PDIA3 expression was positively correlated with HCK, LCK, MHC-I, MHC-II, STAT1, and interferon, but negatively related to IgG in pan-glioma and GBM analysis based on both TCGA and CGGA datasets." (PMID 32687065, 2020). "In accordance with these observations, high expression of STAT1 and its target genes (e.g., ISG15, ITI44, MX1 and OAS1) is associated with lower survival rates in high-grade glioma." (PMID 30709063, 2019). "Additional study on STAT family members, implicates STAT1 as a tumor suppressor protein in gliomas by inhibiting cell growth and promoting apoptosis, but further investigation is needed." (PMID 31698775, 2019). "This prediction was later partly confirmed by the most recent reports that IDH mutations suppress STAT1 and CD8+ T cell accumulation and downregulate leukocyte chemotaxis in gliomas." (PMID 29643764, 2018).
glioma (continued). "Elucidating the nature of the interaction between PLAC2 and STAT1 can provide a basis for new drugs for glioma treatment." (PMID 28922548, 2018). "Our microarray data revealed that STAT1 was up‐regulated in glioma tissues (fold change = 2.193; P < 0.05), whereas a tandem mass spectrum analysis also identified STAT1 as a potential binding partner of RPL36." (PMID 28922548, 2018). "We found that low STAT1-expressing glioma patients had the best overall survival when compared to high STAT1-expressing patients, with intermediate patients falling somewhere in between in overall survival." (PMID 27705947, 2016). "We also examined the relationship between STAT1 expression in publically available databases on patient survival in glioma." (PMID 27705947, 2016). "Patients bearing STAT1-high glioma had significantly shorter survival than those bearing STAT1-low glioma (p = 0.0009)." (PMID 27705947, 2016). "Taken together, these data indicate that the effect of NMI on glioma cell proliferation is dependent on its regulation of STAT1." (PMID 25669971, 2015). "To explore the role of STAT1 in glioma growth, we assessed proliferation of U251 cells overexpressed or lost STAT1 by CCK-8 assays." (PMID 25669971, 2015). "We found that NMI and STAT1 showed dominant expression in the cytoplasm rather than the nucleus with both of the fluorescent signals merged with each other, indicating the co-localization of NMI and STAT1 within glioma cells." (PMID 25669971, 2015). "Both Stat1 and Stat2 clustered into the glioma-regulated brown module and were around 2.5 fold upregulated." (PMID 25658639, 2015). "For ANXA5, STAT1, CD44, CAV1, and ANXA2, LGG patients with high expression possessed a worse overall survival, while low expression of MAPT was associated with poor overall survival among patients with primary gliomas." (PMID 40607003, 2025). "Mechanistically, studies suggest that SP140 promotes PD-L1 expression through STAT1/IRF1 activation in tumor-associated macrophages, which may explain its association with immune escape and poor prognosis in cancers such as glioma and ccRCC." (PMID 41188771, 2025). "In human glioma cells, STAT1 can abolish HIF-1a activity, thereby reducing VEGF-A expression." (PMID 40370455, 2025). "For example, targeting STAT1 can promote EMT in glioma and lung adenocarcinoma cells." (PMID 39055888, 2024). "Specifically, α-solanine improves the glioma prognosis by down-regulating the expression of STAT1." (PMID 37865727, 2023). "Moreover, STAT1 plays a key role in the glioma malignant phenotype, and STAT1 downregulation can inhibit the aggressiveness of GBM cells by regulating the epithelial–mesenchymal transition (EMT)." (PMID 37759950, 2023). "Finally, STAT1 was identified as a potential mediator of the effect of α-solanine on glioma prognosis." (PMID 37865727, 2023). "A recent study reported that STAT1 has a protumorigenic role in gliomas." (PMID 37865727, 2023). "Furthermore, based on seven clusters of metagenes, GSVA identified that ICOS was tightly associated with HCK, LCK, MHC-I, MHC-II, STAT1, and interferon, especially with LCK, suggesting a strong correlation between ICOS and T-cell activity in gliomas." (PMID 36276141, 2022). "After all, our findings bring the new insight that STAT1 may repress glioma carcinogenesis by modulating MGMT expression." (PMID 34544433, 2021). "However, a more recent study showed that IL-8 promoted glioma migration, invasion, and mesenchymal transition by regulating the STAT1/HIF-1α/Snail axis." (PMID 34276757, 2021).
glioma (continued). "The expression of STAT1/2/3/5A/6 members were significantly higher and positively correlated with IDH mutations, while the expression of STAT5B was lower and negatively correlated with IDH mutations in glioma." (PMID 34276757, 2021). "STAT1 might be a molecular marker for the early detection of glioma, as well as a prognostic factor in the determination of glioma aggressiveness." (PMID 34784299, 2021). "CPVL inhibition induced glioma cell apoptosis via the STAT1 signaling pathway." (PMID 34784299, 2021). "In addition, STAT1 expression in malignant glioma cells regulates tumor cell proliferation, migration, and invasion, and STAT1 level in human GBM tissues has been proposed as a novel prognostic biomarker." (PMID 34771447, 2021). "Conversely, STAT1 or Signal Transducer and Activator of Transcription controls the expression of different proteins involved in cell viability, and its activation has been previously reported to be involved in suppression of glioma carcinogenesis." (PMID 34900729, 2021). "For instance, activation of STAT1 was reported to suppress the proliferation of glioma cells." (PMID 34544433, 2021). "Overexpression of STAT1 strongly suppresses the growth of glioma cells and promotes cell apoptosis." (PMID 34276757, 2021). "These molecular epidemiological results provide logical evidence to support the contention that STAT1 may mediate its tumor suppressor function in glioma by regulating MGMT expression." (PMID 34544433, 2021). "Recently, Gary and colleagues found that IDH1 mutations could suppress STAT1 signaling and CD8+ T cell accumulation to promote the immune evasion ability of gliomas." (PMID 32508015, 2020). "Both total and phosphorylated STAT1 protein was shown to be reduced in IDH1 mutant gliomas, and knockdown of STAT1 in wildtype IDH1 tumors resulted in reduced expression of these chemokines, suggesting that R-2-HG can potentially abrogate cytokine signaling through this pathway." (PMID 31781488, 2019). "We hypothesized that STAT1 would be protumorigenic in glioma, which was consistent with our finding that STAT1 was expressed at high levels in GBM cells lines." (PMID 27705947, 2016). "Furthermore, miR203 expression is inversely related to STAT1 levels in patient samples from glioma, and high STAT1 expression closely correlates with poor patient survival and prognosis." (PMID 27705947, 2016). "Moreover, we also demonstrated that the NMI induced glioma cell proliferation was dependent on STAT1, whereas the differences between the two isoforms of STAT1 were not well understood." (PMID 25669971, 2015). "To test our hypothesis, we evaluated whether STAT1 could alter the effect of NMI on glioma cell growth." (PMID 25669971, 2015). "In contrast, depletion of STAT1 expression could dramatically inhibit glioma cell growth in comparison with the control." (PMID 25669971, 2015). "Given the role of NMI in regulation of glioma cell growth and STAT1 expression and regulatory role of STAT1 in glioma cell proliferation, we hypothesized that NMI may affect glioma cell growth via regulation of STAT1." (PMID 25669971, 2015). "The results showed that IgG, HCK, MHC-II, LCK, STAT1 interferon, B7-CD28, and TNF-related tumor immune responses were significantly enhanced with the increasing risk scores, indicating that the immune microenvironment in high-risk glioma patients regulates response changes." (PMID 37228500, 2023). "Gliomas in orthotopic syngeneic glioma mouse models bearing the IDH1 mutation compared with gliomas in mice wild type (WT) for IDH1 also have reduced tumor-infiltrating cytotoxic T cells, as well as reduced chemokine CXCL10 expression and reduced STAT1-positive cells." (PMID 35385679, 2022). "However, CPVL induced apoptosis in glioma cells through the IFN-γ/STAT1 signaling pathway." (PMID 35754804, 2022).
glioma (continued). "In addition, there are clearly other forms of cancer besides glioma where the miR203/STAT1 pathway may play an important role." (PMID 27705947, 2016). "Hence, we assessed the relationship between NMI and STAT1 in glioma." (PMID 25669971, 2015). "It inhibited the glioma cell apoptosis by interacting with BTK and downregulating STAT1 phosphorylation through the facilitation of p300-mediated STAT1 acetylation." (PMID 38962317, 2024). "In glioma, HOXA-AS2 affects the expression of E2F8, E2F1, ATF3, and STAT1, promoting the proliferation of glioma stem cells (GSCs) and enhancing their aggressiveness." (PMID 38311789, 2024). "The top five TFs with the highest correlations in both datasets consisted of STAT1, MEOX2, CREM, NR2F2, and IRF3, indicating that they were likely to regulate the expression of SERPINF1 in glioma." (PMID 36980858, 2023). "The results showed that STAT1, CREM, and NR2F2 were the most likely upstream TFs of SERPINF1 in glioma." (PMID 36980858, 2023). "Recently, mutations in the enzyme cytosolic isocitrate dehydrogenase (IDH1) were discovered to inhibit STAT1 signaling to induce CD8+ T cell accumulation, thereby promoting immune evasion in gliomas." (PMID 35222387, 2022). "LncRNA PLAC2 inhibits the nuclear translocation of STAT1, thus reducing RPL36 expression, inhibiting glioma cell proliferation, and inducing cell cycle arrest." (PMID 35113786, 2022). "STAT1, STAT3, STAT5A, STAT5B, and STAT6 mRNA expression levels were significantly upregulated in glioma (including GBM, astrocytoma, oligodendroglioma, and anaplastic astrocytoma), compared with normal brain tissues or neural stem cells." (PMID 34276757, 2021). "The LFS patient had the highest level of STAT1 and STAT2 expression in an institutional high-grade glioma cohort of 45 patients, further supporting the cancer compendium results." (PMID 34943910, 2021). "Collectively, our study demonstrates that CPVL directly interacts with BTK to downregulate the STAT1 phosphorylation through promoting p300-mediated STAT1 acetylation, supporting the pursuit of CPVL as a potential target for glioma intervention." (PMID 34784299, 2021). "CPVL suppressed glioma cell apoptosis by physically interacting with BTK and downregulating the STAT1 phosphorylation through promoting p300-mediated STAT1 acetylation." (PMID 34784299, 2021). "We observed decreased overall expression and activation of signal transducer and activator of transcription 1 (STAT1) and significantly lower levels of the effector T-cell attracting chemokines, such as CXCL10, produced by IDH-mutant glioma cells." (PMID 30740109, 2018). "The protein-protein interaction (PPI) network analysis showed that ANXA5, STAT1, CD44, CAV1, ANXA2, and MAPT may serve as candidate biomarkers in glioma diagnosis." (PMID 40607003, 2025). "In summary, a systematic bioinformatics analysis of DEGs demonstrated that ANXA5, STAT1, CD44, CAV1, MAPT, and ANXA2 might serve as potential biomarkers and therapeutic targets for glioma." (PMID 40607003, 2025). "Altogether, these findings suggested that ANXA5, STAT1, CD44, CAV1, MAPT, and ANXA2 might play a vital role in the pathogenesis of gliomas." (PMID 40607003, 2025). "Generally, these results suggested that ANXA5, STAT1, CD44, CAV1, MAPT, and ANXA2 might play a critical role in the pathogenesis of glioma, suggesting that the hub genes might be a promising biomarker of glioma." (PMID 40607003, 2025). "Finally, six genes (ANXA5, STAT1, CD44, CAV1, MAPT, and ANXA2) with the highest degree values were selected as the hub genes for glioma by using the cytoHubba plugin for expression level and prognosis analyses." (PMID 40607003, 2025).
glioma (continued). "Hence, the mechanism of how ANXA5, STAT1, CD44, CAV1, MAPT, and ANXA2 contributed to the gliomas still need further research." (PMID 40607003, 2025). "Research has reported that EGF could induce STAT1 expression to exacerbate the IFN-γ-mediated PD-L1 axis in EGFR-positive cancer cell lines, excluding glioma, and blockade of EGFR by afatinib inhibited EGF- and IFN-γ-mediated PD-L1 expression." (PMID 37759950, 2023). "Moreover, STAT1 was the only hub target significantly correlated with the overall survival (OS) and disease-free survival (DFS) of glioma patients." (PMID 37865727, 2023). "We then further investigated the effects of ALKBH5 expression on the tumor immune microenvironment (TIM) of glioma by screening seven metagenes, namely, HCK, IgG, Interferon, LCK, MHC-I, MHC-II, and STAT1, which reflect the status of inflammation and immune responses." (PMID 35444654, 2022). "We discovered that LIGHT expression exhibited a positive correlation with HCK, interferon, LCK, MHC-I, MHC-II, and STAT1 metagenes in all gliomas, while IgG exhibited a negative correlation with LIGHT expression based on the TCGA and CGGA datasets." (PMID 36341396, 2022). "Previously, we have shown that STAT1/IRF-1 signaling was involved in the development of bevacizumab resistance (often mesenchymal), and that genetic inhibition of IRF1 increased apoptosis in bevacizumab-treated glioma cells." (PMID 34771447, 2021). "It has also been reported that autocrine IFN signaling is constitutively active in glioma tumors and glioma non-stem cells, and malignant glioma cells expressed high STAT1, which influences tumor cell proliferation, migration, and invasion." (PMID 34771447, 2021). "Consequently, TNFSF13 expression was identified positively correlated with interferon, STAT1, MHC-I, MHC-II, HCK, and LCK, while negatively relevant to IgG metagene in pan-glioma analysis and GBM alone analysis in both TCGA and CGGA databases." (PMID 34712225, 2021). "Through suppressing the molecule, called signal transducer and activator of transcription 1 (STAT1), D-2-HG could result in a reduction of CD8 + T-cell immigration into the glioma region." (PMID 34650972, 2021). "Lack of NFκB activation and interferon-dependent Stat1 phosphorylation was demonstrated in microglial cultures exposed to rat C6 glioma." (PMID 26427514, 2015). "Considering that NMI has been reported to interact with various proteins, it is reasonable to assume that besides STAT1, other interactors of NMI may also be involved in development and progression of human glioma, which warrant further investigation." (PMID 25669971, 2015). "Furthermore, to confirm the interaction of NMI and STAT1, a co-IP assay was applied, in which U251 glioma cells were infected with lentiviruses carrying Flag-tagged NMI and STAT1 expressing vectors while empty vector served as a control." (PMID 25669971, 2015). "Collectively, these data suggest that NMI and STAT1 not merely interact with each other in glioma cells, but have a mutual regulation." (PMID 25669971, 2015). "To better understand how α-solanine exerts its therapeutic effects through the hub target STAT1 and improves the prognosis of glioma patients, we conducted a GSEA analysis to identify potential biological signalling pathways affected by the overexpression of STAT1 in glioma." (PMID 37865727, 2023). "Furthermore, STAT1, CREM, and NR2F2 may participate in the transcriptional regulation of SERPINF1 in glioma." (PMID 36980858, 2023). "In addition, we provide evidence that STAT1 directly binds to SH2B3 promoter and activates its expression in the transcriptional level, which in turn activates STAT3, thereby facilitating glioma progression." (PMID 33937225, 2021).